SNORA22 (small nucleolar RNA, H/ACA box 22)
Synonyms: ACA22; SNORA22A
Gene: Small nucleolar RNA gene on chromosome 7 (65,755,526 to 65,755,659, forward strand). Ensembl gene ENSG00000206634.
Gene Ontology:
Biological process: RNA processing
Cellular component: nucleolus
Homologues: Orthologues: mouse Gm23245 (87% identical), rat Snora22c (87% identical). Paralogues in human: SNORA22C (99% identical), SNORA22B (95% identical).
Diseases named in the same sentence as SNORA22 in open-access papers:
SNORA22 is named in the same sentence as 3 diseases in open-access papers, as found by Europe PMC text mining. Sharing a sentence is not in itself a finding about the gene and the disease. The quoted sentences say what the papers report.
Arthritis (1 paper, 2022). Inflammation of a joint. "The overexpression of SNORA22 positively correlated with arthritis because it contributes to cell invasion and tumor metastasis, while cell erosion can aggravate the disease manifestations of RA43." (PMID 35864275, 2022). "Furthermore, the expression of Tnnil1, Gpnmb, Mypn and Acsl6 was positively correlated to the paw diameter (paw swell) while the expression of SNORA22 and Acsl6 was positively correlated to the arthritis score (P < 0.05)." (PMID 35864275, 2022).
pancreatic cancer (1 paper, 2025). "Additionally, through its interactions with the small nucleolar RNAs SNORA18 and SNORA22, KSRP has been demonstrated to promote the invasiveness and metastasis of pancreatic cancer cells." (PMID 40699755, 2025).
tumor (2 papers, 2020 to 2022). "Consequently, SNORA18 and SNORA22 contributed to cell invasiveness and tumor metastasis." (PMID 32010427, 2020).